RPTOR (regulatory associated protein of MTOR complex 1)
Description:
Component of the mechanistic target of rapamycin complex 1 (mTORC1), an evolutionarily conserved central nutrient sensor that stimulates anabolic reactions and macromolecule biosynthesis to promote cellular biomass generation and growth. In response to nutrients, growth factors or amino acids, mTORC1 is recruited to the lysosome membrane and promotes protein, lipid and nucleotide synthesis by phosphorylating several substrates, such as ribosomal protein S6 kinase (RPS6KB1 and RPS6KB2) and EIF4EBP1 (4E-BP1). In the same time, it inhibits catabolic pathways by phosphorylating the autophagy initiation components ULK1 and ATG13, as well as transcription factor TFEB, a master regulators of lysosomal biogenesis and autophagy. The mTORC1 complex is inhibited in response to starvation and amino acid depletion. Within the mTORC1 complex, RPTOR acts both as a molecular adapter, which (1) mediates recruitment of mTORC1 to lysosomal membranes via interaction with small GTPases Rag (RagA/RRAGA, RagB/RRAGB, RagC/RRAGC and/or RagD/RRAGD), and a (2) substrate-specific adapter, which promotes substrate specificity by binding to TOS motif-containing proteins and direct them towards the active site of the MTOR kinase domain for phosphorylation. mTORC1 complex regulates many cellular processes, such as odontoblast and osteoclast differentiation or neuronal transmission (By similarity). mTORC1 complex in excitatory neuronal transmission is required for the prosocial behavior induced by the psychoactive substance lysergic acid diethylamide (LSD) (By similarity).
Synonyms: Raptor; KIAA1303; KOG1; Mip1
Tractability: Small molecule: a drug acting on it is in phase 2 or 3 trials; a structure with a bound ligand is known; a high-quality ligand is known. PROTAC: UniProt records ubiquitination sites on it; ubiquitination databases record sites on it; its protein half-life has been measured; a small molecule that binds it is known.
Safety:
Unwanted effects reported when the protein is acted on. In parentheses: how it was acted on, where the effect was seen, and who reports it.
pneumonitis (source: ClinPGx)
progression-free survival (source: ClinPGx)
Gene: Protein-coding gene on chromosome 17 (80,544,819 to 80,966,371, forward strand). Ensembl gene ENSG00000141564.
Subcellular location: Lysosome membrane; Cytoplasm; Cytoplasmic granule
Subcellular location (Human Protein Atlas): Lysosomes; Vesicles; Cytosol
Pathways (Reactome):
Signal Transduction: Energy dependent regulation of mTOR by LKB1-AMPK; MTOR signalling; Regulation of PTEN gene transcription; mTORC1-mediated signalling
Cellular responses to stimuli: Amino acids regulate mTORC1; HSF1-dependent transactivation
Autophagy: Macroautophagy
Disease: Dengue virus modulates apoptosis
Gene Ontology:
Molecular function: 14-3-3 protein binding; enzyme-substrate adaptor activity; protein binding; protein kinase activator activity; protein kinase binding; protein serine/threonine kinase activity; protein serine/threonine kinase inhibitor activity; protein-containing complex binding; protein-macromolecule adaptor activity; small GTPase binding
Biological process: cellular response to amino acid stimulus; cellular response to glucose stimulus; cellular response to L-leucine; cellular response to nutrient levels; negative regulation of autophagy; positive regulation of cell growth; positive regulation of G1/S transition of mitotic cell cycle; positive regulation of TOR signaling; positive regulation of transcription by RNA polymerase III; regulation of cell growth; regulation of cell size; TOR signaling; TORC1 signaling; cellular response to hypoxia; cellular response to osmotic stress; cellular response to starvation; DNA damage response; positive regulation of glycolytic process; positive regulation of lipid biosynthetic process; positive regulation of odontoblast differentiation; positive regulation of osteoclast differentiation; positive regulation of pentose-phosphate shunt; response to xenobiotic stimulus; social behavior; positive regulation of endothelial cell proliferation; and 2 more
Cellular component: cytoplasm; cytoplasmic stress granule; cytosol; lysosomal membrane; lysosome; TORC1 complex; nucleoplasm; dendrite; neuronal cell body
Genetic constraint (gnomAD): Loss-of-function variants: 20 observed, 141.76 expected, observed/expected ratio (o/e) 0.14, 90% interval 0.098 to 0.2. The upper end of that interval is the gene's LOEUF score, 0.2, which puts it in group 1 of 6, group 1 being the genes least tolerant of losing a copy. Missense variants: 1,086 observed, 1,775.3 expected, observed/expected ratio (o/e) 0.61, 90% interval 0.58 to 0.64. Synonymous variants: 700 observed, 729.09 expected, observed/expected ratio (o/e) 0.96, 90% interval 0.9 to 1.02.
Homologues: Orthologues: macaque RPTOR (99% identical), chimpanzee RPTOR (98% identical), guinea pig RPTOR (97% identical), rat Rptor (97% identical), mouse Rptor (97% identical), dog RPTOR (96% identical), pig RPTOR (96% identical), tropical clawed frog rptor (91% identical), zebrafish rptor (88% identical), Drosophila melanogaster raptor (48% identical), Caenorhabditis elegans daf-15 (35% identical).
Diseases named in the same sentence as RPTOR in open-access papers:
RPTOR is named in the same sentence as 78 diseases in open-access papers, as found by Europe PMC text mining. Sharing a sentence is not in itself a finding about the gene and the disease. The quoted sentences say what the papers report.
Obesity (11 papers, 2014 to 2024). Accumulation of substantial excess body fat. "RPTOR has previously been directly associated with obesity in several genome-wide association studies (GWAS) and epigenome-wide association studies (EWAS)." (PMID 37513594, 2023). "KCNQ1 and RPTOR, which showed differences between lean and obese women at many methylated sites, have both been linked to obesity in earlier studies." (PMID 30397228, 2018). "Many genes on this list are involved in different processes associated with T2DM development, such as obesity (SREBF1 and H6PD), inflammation (TGFB1), and insulin resistance (RPTOR and AKT1)." (PMID 39273245, 2024). "Pyrosequencing results validated the association of SETD8, SLIT3, and RPTOR methylation with GWG and showed that higher levels of SETD8 and RPTOR methylation and lower levels of SLIT3 methylation relate to a higher risk of obesity in the offspring." (PMID 37513594, 2023). "Methylation loci associated with obesity (AEBP2), calcium signaling (CAPNS1), insulin signaling (INSR, PTPRN2, RPTOR) and vasodilation (VASP) also appeared to be epigenome-wide significant." (PMID 29692868, 2018). "These genes include CD36 (HDL-C), RPTOR (obesity) and ABCG5/ABCG8 (low-density lipoprotein cholesterol (LDL-C) and total cholesterol)." (PMID 26021296, 2015). "In addition to the findings of these immune-regulatory genes, many other top associations have been implicated in obesity (AEBP2) (FDR < 0.10), calcium signaling (CAPNS1), insulin signaling (INSR, PTPRN2, RPTOR), and vasodilation (VASP)." (PMID 29692868, 2018).
breast carcinoma (9 papers, 2016 to 2022). "Recent studies have linked RPTOR activity with treatment implications in triple-negative and luminal-A breast cancer models." (PMID 34788626, 2021). "We previously identified the mTOR pathway components RHEB and RPTOR as being positively regulated by EVI1 in metastatic breast cancer with stem cell-like features." (PMID 32012804, 2020). "Previous findings for cg06418238 in RPTOR, cg00736299 in MGRN1, and cg27466532 in RAPSN that were recently reported to be associated with breast cancer risk were not replicated by our study." (PMID 31101124, 2019). "An analysis published after the systematic review reported CpG sites cg06418238 in RPTOR, cg00736299 in MGRN1, and cg27466532 in RAPSN to be more commonly hypomethylated in breast cancer cases, although these associations were not replicated by the Melbourne Collaborative Cohort Study (MCCS)." (PMID 31101124, 2019).
esophageal squamous cell carcinoma (8 papers, 2022 to 2026). Esophageal squamous cell carcinoma (ESCC) is a type of esophageal carcinoma (EC) that can affect any part of the esophagus, but is usually located in the upper or middle third. "METTL1 is significantly up-regulated in esophageal squamous cell carcinoma, and its mediated tRNA m7 G modification promotes malignant progression of esophageal squamous cell carcinoma through the RPTOR/ULK 1/autophagy axis, and its high expression is associated with poor prognosis of patients." (PMID 39289775, 2024). "Previous reports have shown that METTL1 promotes esophageal squamous cell carcinoma through the RPTOR/ULK1/autophagy axis and mediates m7G tRNA modification to promote lenvatinib resistance in hepatocellular carcinoma." (PMID 38822363, 2024). "RPTOR/ULK1/autophagy axis influence esophageal squamous cell carcinoma tumorigenesis." (PMID 38240686, 2024). "For example, in esophageal squamous cell carcinoma (ESCC), METTL1 promotes tumor progression through the regulation of RPTOR gene translation." (PMID 41501031, 2026). "In esophageal squamous cell carcinoma (ESCC), researchers demonstrated that METTL1 and WDR4 could induce the translation of RPTOR and decrease autophagic flux in ESCC cells." (PMID 38385078, 2024).
colorectal cancer (7 papers, 2018 to 2025). A primary or metastatic malignant neoplasm that affects the colon or rectum. "Meanwhile, RPTOR, a crucial component of the mTOR pathway, regulates cell growth in response to nutrient and insulin levels and has been reported as a key driver gene in the brain metastasis of lung and colorectal cancer progression." (PMID 41226303, 2025). "Another long-lived mammals-specific positive selection gene—RAPTOR (Regulatory associated protein of mTOR complex 1) was responsible for the induction of mTORC1 during tumorigenesis and progression, such as RAPTOR overexpression in colorectal cancer tissues and cell lines." (PMID 37582720, 2023).
melanoma (7 papers, 2015 to 2024). A malignant, usually aggressive tumor composed of atypical, neoplastic melanocytes. "Interestingly, the PI3K-Akt signaling pathway shared all genes enriched in melanoma pathway (e.g., CDK6, FGF20, and MITF) and included three additional genes (i.e., RPTOR, COMP, and CDC37), suggesting a higher level of significance and potential relevance." (PMID 37829282, 2023).
lung carcinoma (4 papers, 2014 to 2024). "As mLST8 and RPTOR are important components of mTORC1, these findings strongly suggest that RPTOR might be implicated in the brain metastasis of lung cancer." (PMID 38163890, 2024). "The SPHK2 inhibitor, ABC294640, also reversed the RPTOR overexpression-increased migration and invasion of lung cancer cell lines and the permeability of BBB models." (PMID 38163890, 2024). "We found that RPTOR promoted the cerebral invasion of the NSCLC lung cancer cells by the SPHK2/S1P/STAT3 axis." (PMID 38163890, 2024). "Transwell assays also showed that RPTOR expression was positively correlated with the migration and invasion of lung cancer cell lines." (PMID 38163890, 2024). "As expected, KM plotter analysis showed that lung cancer patients who highly expressed ERK, AKT, c-myc, 4EBP1, RPTOR (regulatory associated protein of mTOR complex 1) and RICTOR (RPTOR independent companion of mTOR complex 2) has a shorter survival time." (PMID 34421360, 2021). "Well-documented as it may be, the involvement of RPTOR in the BM of lung cancer has been barely reported." (PMID 38163890, 2024). "RPTOR is a key driver gene in the brain metastasis of lung cancer, which signifies that RPTOR blockade may serve as a promising therapeutic candidate for clinical application." (PMID 38163890, 2024). "Therefore, we hypothesized that RPTOR may promote the brain metastasis of lung cancer through the SPHK2/S1P/STAT3 axis." (PMID 38163890, 2024). "Finally, Co-IP assays showed mutual interactions between RPTOR and YY1 in these lung cancer cell lines." (PMID 38163890, 2024). "After RPTOR interference or overexpression, the in vitro assays, including Cell Counting Kit-8 (CCK8), clone formation assay, and wound healing, reported that RPTOR positively impacted the migration, invasion and proliferation of lung cancer cell lines." (PMID 38163890, 2024). "The addition of the SPHK2 inhibitor, ABC294640, to the RPTOR-overexpressed PC9 cells significantly inhibited the RPTOR-induced activation of the SPHK2/S1P/STAT3 signaling pathway and restrained the RPTOR overexpression-enhanced proliferation, migration and invasion of lung cancer cell lines." (PMID 38163890, 2024).
bladder cancer (3 papers, 2018 to 2024). "Data identified that in the low HER2 cohort and different ATM levels (high/low); ABL1, SMAD4, RB1 and PARP1 were significantly upregulated and AKT1, AKT2, TSC2, RPTOR and mTOR were significantly downregulated in bladder cancer." (PMID 36056635, 2022).
Hepatic steatosis (3 papers, 2020 to 2023). Steatosis is a term used to denote lipid accumulation within hepatocytes. "In rodent models, RPTOR deletion in adipocytes diminishes white adipose tissue (WAT) and promotes lipolysis and gradual lipodystophy with a parallel lipid accumulation in the liver, developing hepatic steatosis, hepatomegaly, and insulin resistance." (PMID 36986146, 2023).
psoriasis (3 papers, 2014 to 2025). An autoimmune condition characterized by red, well-delineated plaques with silvery scales that are usually on the extensor surfaces and scalp. "Nevertheless, mTOR signalling is hyper-activated in psoriatic lesions and altered expression of RPTOR may contribute to psoriasis susceptibility." (PMID 39145956, 2024). "Our results do not support the literature data pointing at RPTOR gene as associated with psoriasis development." (PMID 24005976, 2014). "There are two reports suggesting an association between RPTOR polymorphisms and psoriasis and one indicating that such association does not exist." (PMID 24005976, 2014). "We ascertain no connection of RPTOR and ZNF750 variants with psoriasis or its subphenotypes." (PMID 24005976, 2014). "Study results do not add evidence of RPTOR and ZNF750 as psoriasis susceptibility genes." (PMID 24005976, 2014). "We ascertain no connection of RPTOR and ZNF750 variants with psoriasis." (PMID 24005976, 2014).
tuberous sclerosis (3 papers, 2015 to 2025). Hereditary disease characterized by seizures, intellectual disability, developmental delay, and skin and ocular lesions. "RPTOR (Regulatory Associated Protein Of MTOR Complex 1) is a protein associated with tuberous sclerosis 1 and tuberous sclerosis." (PMID 35428183, 2022).
Hyperglycemia (2 papers, 2017 to 2023). An increased concentration of glucose in the blood. "Taken together, these findings in tissue-specific cells show that hyperglycemia converges on major insulin, lipid, and fibrosis pathways by DNA methylation to regulate the expression of core genes that consist of but are unlikely to be limited to MTOR, RPTOR, IRS2, TXNRD1, LCAT, SMPD3, and COL1A2." (PMID 36633903, 2023).
osteoporosis (2 papers, 2018 to 2019). A condition of reduced bone mass, with decreased cortical thickness and a decrease in the number and size of the trabeculae of cancellous bone (but normal chemical composition), resulting in increased fracture incidence. "The regulatory action of RPTOR to skeletal tissue metabolism and osteoporosis pathogenesis seems like inconclusive." (PMID 30224697, 2018).
dilated cardiomyopathy (1 paper, 2023). Cardiomyopathy which is characterized by dilation and contractile dysfunction of the left and right ventricles. "Genetic deficiency of RPTOR, regulatory-associated protein of mTOR Complex 1 (mTORC1), leads to reduction mTORc1 activity and development of dilated cardiomyopathy in mice." (PMID 36656640, 2023).
dysferlinopathy (1 paper, 2023). "Analysis of muscle transcripts from patients with dysferlinopathy helped identify the following 7 upregulated DEGs involved in the cellular response to stress: HSPA9, RPTOR, MTOR, LAMTOR1, LAMTOR5, ATP6V0D1, and ATP6V0B." (PMID 38125829, 2023).
food allergy (1 paper, 2018). Gastrointestinal disturbances, skin eruptions, or shock due to allergic reactions to allergens in food. "Of these, 3/87 SNPs in the RPTOR gene (rs9906827, rs2672886, rs9908768) showed weak evidence of an association (P = 0.070, P = 0.047, P = 0.093) with food allergy." (PMID 30120223, 2018).
gastric cancer (1 paper, 2021). A primary or metastatic malignant neoplasm involving the stomach. "A study of gastric cancer patients detected a high frequency of mutations in MLL4, ERBB3, FBXW7, MLL3, mtor(RPTOR), NOTCH1, PIK3CA, KRAS, ERBB4 and EGFR." (PMID 33909629, 2021).
malignant mesothelioma (1 paper, 2023). A malignant neoplasm of the pleura or peritoneum, arising from mesothelial cells. "Expression profiles of malignant mesotheliomas revealed that 46% displayed altered expression of RPTOR (mTORC1 component) that activates the mechanistic target of rapamycin complex 1 (mTORC1) to enhance MM cell growth suggesting the worse outcome of nuclear DAMPs subtype." (PMID 37033966, 2023).
myocardial infarction (1 paper, 2021). Gross necrosis of the myocardium, as a result of interruption of the blood supply to the area, as in coronary thrombosis. "In this study, we identified 30 MOFA factors and 10 were associated with myocardial infarction; one of them included three genes that were also included in the factor 27 of the FOS cohort: CDC42BPB, MAN2A2, and RPTOR." (PMID 33836805, 2021). "Moreover, in a replication effort in an independent study three of the genes included in factor 27 were also present in a factor identified to be associated with myocardial infarction (CDC42BPB, MAN2A2 and RPTOR)." (PMID 33836805, 2021).
myopia (1 paper, 2019). "RPTOR and VAMP2 are two more genes identified in our study under insulin receptor signaling and were hypermethylated with a significant association with myopia." (PMID 30858441, 2019).
non-small cell lung carcinoma (1 paper, 2024). A group of at least three distinct histological types of lung cancer, including non-small cell squamous cell carcinoma, adenocarcinoma, and large cell carcinoma. "Xenograft and zebrafish model showed that RPTOR blockade suppressed BM of non-small cell lung cancer (NSCLC) and impaired the SPHK2/S1P/STAT3 pathway." (PMID 38163890, 2024).
oral cancers (1 paper, 2018). "MAPKAP1, TSC1 and RPTOR are also involved in mTOR signaling, which has been associated with tumor growth and immune regulation in the local microenvironment of oral cancers." (PMID 30308005, 2018).
skin cancer (1 paper, 2021). "Another special case seems to be skin cancer cell line LIWE, which showed downregulation after monotherapy (KI or IR) of Cyclin D1, RPTOR, and Myc in obvious contrast to the upregulation after combination of KI and IR." (PMID 34722291, 2021).
type 2 diabetes (1 paper, 2021). "Among the hub genes screened, four genes (NEUROG3, TCF7L2, MAP2K5 and RPTOR) were validated as showing the upregulated expression pattern in blood samples in type 2 diabetes cases." (PMID 34830198, 2021).